SMAD2 (SMAD family member 2)
Diseases named in the same sentence as SMAD2 in open-access papers (continued):
Sharing a sentence is not in itself a finding about the gene and the disease.
keloid (18 papers, 2013 to 2025). An irregularly shaped, elevated mark on the skin caused by deposits of excessive amounts of collagen during wound healing. "In detail, it has previously been found that ATF3 induces proliferation and invasion and inhibits apoptosis via TGFβ1/SMAD2/3 signalling in keloid fibroblasts." (PMID 38256034, 2024). "According to one study, the p38MAPK inhibitor significantly disrupted the Smad2/3/4 complex formation and thus decreased the invasiveness of keloid FBs." (PMID 35858881, 2022). "We previously showed that silencing of the TGF-β family member GDF-9 in keloid-derived fibroblasts downregulated p-Smad2 and p-Smad3." (PMID 33628711, 2021). "Pivotal mediators of the TGF-β signaling pathway, the Smad2/3 and ERK1/2 complexes, are highly activated in keloids and have been implicated in keloid pathogenesis." (PMID 31450620, 2019). "Hypoxia up-regulated TGF-β1, Smad2/3, p-Smad2/3, Smad4, and total collagen in both normal and keloid fibroblasts via HIF-1α, which was attenuated by HIF-1α inhibition, but TβRII levels were not significantly altered." (PMID 29423039, 2018). "Immunohistochemistry staining showed higher protein levels of HIF-1α and Smad2/3 in keloid dermis than those in normal dermis." (PMID 29423039, 2018). "In a separate study, we showed that growth differentiation factor- (GDF-) 9 promoted fibroblast proliferation and migration in keloids via the Smad2/3 pathway, while others have demonstrated that TGF-β/Smad signaling plays an essential role in the development of keloids." (PMID 33628711, 2021). "Besides, the overexpression of miR-133a-3p can suppress fibrosis by down-regulating IRF5 and then inhibiting the TGF-β/Smad2 signaling pathway, therefore, promoting apoptosis and reducing the proliferation in keloid fibroblasts." (PMID 34225723, 2021). "Indeed, immunohistochemical analysis in the keloid sections showed intense phosphorylated forms of Smad2/Smad3, which are central mediators of intracellular TGF-β signal transduction." (PMID 27339758, 2016). "In addition, the keloid sections were incubated with antibodies against Phospho-Smad2/Smad3, Phospho-Erk1/2, CD31, CD34, collagen I, and collagen III at a dilution of 1:500." (PMID 27339758, 2016). "Moreover, the down-regulation of Smad2 expression in keloid fibroblasts can significantly decrease procollagen gene expression." (PMID 23418473, 2013). "Future studies should further confirm this by treating primary keloid fibroblasts with THZ1 and detecting Smad2 C-terminal phosphorylation levels." (PMID 41347148, 2025). "Here, we provide further evidence that Smad2/3 signaling and the upregulation of TGF-β receptors are directly involved in keloid pathogenesis." (PMID 33628711, 2021). "More importantly, we show that LY2109761, a TGF-β receptor inhibitor, negatively regulated the Smad2/3 signaling pathway and downregulated the expression of TGF-β1 in keloid-derived fibroblasts." (PMID 33628711, 2021). "We found that the expression of TGF-β and the Smad2/3 and ERK1/2 complexes was significantly attenuated by glycyrrhizin in keloid spheroids." (PMID 31450620, 2019). "We next determined the effect of glycyrrhizin on TGF-β, Smad2/3, and ERK1/2 expression in keloid spheroids; these molecules are crucial regulators of fibrogenesis." (PMID 31450620, 2019). "Aberrant activation of TGFß signaling has also been implicated in scleroderma fibrosis and in keloid, a fibrotic disease characterized by abnormal accumulation of ECM in the dermis via reduction in TGFß/p-SMAD-2." (PMID 23437361, 2013). "TGF-β, Smad2/3, ERK1/2, and HMGB1 were decreased in glycyrrhizin-treated keloids." (PMID 31450620, 2019). "Additionally, SNPs in TGFBR1 (e.g., rs334348) increase Smad2/3 phosphorylation and promote fibroblast‐to‐myofibroblast differentiation, a transition widely observed in the hypercontracting and fibrotic phenotypes of fibroblasts isolated from HTS and keloids." (PMID 41049267, 2025).
keloid (continued). "Although CTHRC1 inhibits TGF-β signaling, which induces phosphorylation of Smad2/3 in smooth muscle cells and collagen type I expression in keloid fibroblasts, we could not confirm such an inhibitory effect in SW480-CTHRC1 cells (data not shown)." (PMID 24504172, 2014).
heart failure (17 papers, 2013 to 2026). Inability of the heart to pump blood at an adequate rate to meet tissue metabolic requirements. "From the perspective of clinical translation, targeting Meox1/Cthrc1/p-Smad2/3 axis offers novel therapeutic potential for treating heart failure and improving the outcomes in patients with MI." (PMID 41362745, 2026). "From the clinical translational perspective, the present study suggests that Meox1/Cthrc1/p-Smad2/3 signaling pathway is a promising prognostic and therapeutic target for post-MI cardiac fibrosis and heart failure." (PMID 41362745, 2026). "DAPA inhibits the increase in α-SMA, TGF-β, Smad2, and Smad3 levels in the myocardial tissues of aortic constriction-induced heart failure model rabbits." (PMID 41392217, 2025). "SDC-1 was reported to function in heart failure by promoting fibrosis through TGF-β/Smad2 or p38/MAPK pathway." (PMID 36078037, 2022). "However, recent studies consistently implicate activin receptor–mediated SMAD2/3 signaling as a partially compensatory pathway that becomes maladaptive in heart failure and ischemia-reperfusion injury." (PMID 36910526, 2023). "Direct inhibition of TGF-β1, SMAD2/3, or TβRI/II will end up with poor outcomes like autoimmune diseases, heart failure, or unknown risks." (PMID 34521301, 2021). "We demonstrate here that mice with calreticulin overexpression, which were used to model heart failure, developed extensive cardiac fibrosis due to transient activation of UPR which in turn underlies the subsequent stimulation of the TGFβ1/Smad2/3 signaling pathway." (PMID 27441395, 2016). "Taken together, our results demonstrated that inhibiting Meox1/Cthrc1/p-Smad2/3 signaling suppressed CFs-to-Myofbs conversion and prevented fibrotic remodeling and heart failure, which may provide clinical translational implications for improving the prognosis of MI patients." (PMID 41362745, 2026). "Similar to our results, losartan reduced cardiac fibrosis in heart failure by reducing the CTGF and SMAD2/3 expression in other studies." (PMID 34884782, 2021).
Hypertension (17 papers, 2015 to 2026). The presence of chronic increased pressure in the systemic arterial system. "In the recent work we proved that FGY-1153 caused a significant inhibition in hypertension-induced activation of TGF and Smad-2 pathways in both myocardium and vascular walls." (PMID 31178756, 2019). "The experiment demonstrated the essential role of TGF‐β/Smad2/3 signaling pathway in vascular remodeling and revealed that inhibition of vascular remodeling may become a new therapeutic strategy to inhibit the progression of hypertensive diseases." (PMID 38018603, 2023). "Following the onset of hypertension (SHR bladder), markers such as HIF-1α, AT1, detrusor collagen, NGF, and TGF-β1/SMAD2/3 are upregulated, leading to increased fibrosis, reduced contractility, and decreased bladder capacity, while VEGF, MAS receptor (MASr), and antioxidants are decreased." (PMID 42162196, 2026). "In the present study, we found that hypertension stimulated CXCR2 activation, which activated several downstream signalling pathways, including NF‐κB, NADPH oxidase and TGF‐β1/Smad2/3, which promoted pro‐inflammatory, pro‐oxidative and pro‐fibrotic effects that led to AF." (PMID 32812337, 2020). "Regarding SHRs, it should be noted that the levels of TGF-β1 were lower, SMAD2/3 were similar, and MMP-2 along with collagen deposition were higher than those observed in WKRs; this most likely reflects the adaptation of 12-month-old SHRs to hypertension." (PMID 31374823, 2019).
endometrial cancer (16 papers, 2015 to 2025). Primary or metastatic malignant neoplasm involving the endometrium (mucous membrane that lines the endometrial cavity). "More importantly, nuclear SMAD2/3 in PTEN-deficient mouse endometrial cancer is extensible to human endometrium." (PMID 34638474, 2021). "Finally, we sought to investigate whether PTEN deficiency led to nuclear localization of SMAD2/3 in human endometrial carcinomas." (PMID 34638474, 2021). "For example, INHBB expression is significantly elevated in endometrial carcinoma tissues and enhances cancer cell invasion by activating the SMAD2/3 and integrin β3 signaling pathways." (PMID 39850875, 2024). "In this study, we observed abnormal differentiation of the endometrium and transformation into endometrial cancer following conditional ablation of the downstream effectors of TGFβ signaling, SMAD2 and SMAD3." (PMID 36906706, 2023). "SMAD2, has been shown to have tumor-suppressive functions in endometrial carcinoma cells, and the inhibition of its activity has been associated with the constituent activation of the PI3K/AKT pathway, increased proliferation and decreased apoptosis." (PMID 37843125, 2023). "SMAD2, SMAD4, and SMAD7 genes are located at the 18q21 locus, which is highly prone to the MSI or loss of heterozygosity (LOH) in endometrial cancer." (PMID 34501347, 2021). "Nonetheless, Smad2 phosphorylated from (pSmad2) staining is undetectable or weak in endometrial cancer and reduced in glandular hyperplasia compared to normal endometrium." (PMID 34501347, 2021). "Smad2 and Smad4 immunoreactivity in endometrial cancer is comparable with that observed in normal endometrium." (PMID 34501347, 2021). "INHBB and activin B are highly expressed in endometrial cancer, and activin B promotes cell adhesion, migration, and invasion via the SMAD2/3/integrin β3 signaling pathway." (PMID 33083477, 2020). "The left-right determination factor (LEFTY) is a novel member of the TGF-β/Smad2 pathway and belongs to the premenstrual/menstrual repertoire in human endometrium, but little is known about its functional role in endometrial carcinomas (Em Cas)." (PMID 29268772, 2017). "It has been shown that in type I endometrial cancers, the levels of SMAD2 phosphorylation are weak or undetectable, and the expression levels of type I and type II TGF-β receptors are decreased." (PMID 27542208, 2016). "Together, these results suggest that classical SMAD2/3-SMAD4 signaling contributes to the down-regulation of PTEN by TGF-β1 in type II endometrial cancer cells." (PMID 27542208, 2016). "Smad2/3/TGF-β signalling has been reported to be involved in EMT in endometrial cancer cell lines." (PMID 36766756, 2023). "A previous study indicated that the TGF-β signaling pathway is implicated in malignant phenotypes in human EC, and activation of the TGF-β/Smad2/3 signaling pathway could enhance endometrial cancer stemness." (PMID 35880567, 2022). "Interestingly, our results suggest that the suppression of PTEN mRNA by TGF-β1 appears to be solely mediated by SMAD2/3-SMAD4 signalling in type II endometrial cancer cells." (PMID 27542208, 2016). "Both preclinical studies demonstrate that ISL could inhibit TGF-β/Smad-induced endometrial cancer cell migration through reducing p-Smad2/3 and TWIST1/2 expression, subsequently decreasing N-cadherin, vimentin, α-SMA while increasing E-cadherin protein expression." (PMID 33799801, 2021). "On the other hand, a study has been published presenting that decreased mRNA levels of SMAD2, SMAD3, and SMAD4 are frequent events, respectively in 71.4%, 78.6%, and 78.6% of analyzed endometrial cancer samples." (PMID 34501347, 2021). "The analysis of human endometrial carcinomas revealed a significant inverse correlation between PTEN expression and SMAD2/3 nuclear staining in Grade III EC." (PMID 34638474, 2021).
endometrial cancer (continued). "Together, our studies suggest that type II endometrial cancer cell migration/invasion involves both MEK-ERK1/2-SNAIL-mediated E-cadherin down-regulation and SMAD2/3-SMAD4-mediated integrin β3 up-regulation." (PMID 27223076, 2016). "We have previously shown that treatment with activin B phosphorylates/activates SMAD2 and SMAD3 in type II human endometrial cancer cells." (PMID 27223076, 2016). "The literature data indicate that SMAD2 and SMAD4 expression is not altered in endometrial cancer when compared to normal endometrium." (PMID 34501347, 2021).
Obesity (16 papers, 2017 to 2026). Accumulation of substantial excess body fat. "In obesity, elevated myostatin levels have been reported to be associated with insulin resistance, muscle atrophy, and activation of SMAD2/3 signaling, while experimental and preclinical studies indicate that myostatin inhibition can improve glucose homeostasis and increase lean mass." (PMID 41596614, 2026). "Obesity increases inflammation and oxidative stress, which are risk factors for frailty syndrome, leading to variations in the expression levels of FoxO3a, Smad2/3, and p62." (PMID 39382189, 2024). "Taken together, the observed increase in p-SMAD2/3 and FOXO1 activity associated with a decline in p-AMKα results in a reduction of mitochondrial function-related genes in obesity, thereby modulating muscle homeostasis and mass." (PMID 41272451, 2025). "Taken together, these data suggested that deletion of FAPs-derived follistatin enhanced MSTN/activin A/p-SMAD2/3 pathway, thereby accelerating skeletal muscle dysfunction in obesity." (PMID 41272451, 2025). "However, obese frailty resulted in a significant decrease in LAMP-2 expression, suggesting that it may regulate LAMP-2 through mechanisms affecting Smad2/3, FoxO3a, and P62 due to the combined effects of frailty syndromes and obesity." (PMID 39382189, 2024). "Signaling impairments in sarcopenic obesity include marked AMPK/PGC-1α suppression, chronic NF-κB/JNK and SMAD2/3 activation, and disrupted autophagy–mitophagy cycles—alterations that synergistically promote IR and metabolic inflexibility." (PMID 41515940, 2025). "Our results suggested that GC improves obesity‐related muscle wasting by activating AKT signaling and suppressing Smad2/3 signaling." (PMID 39055231, 2024). "GC supplementation reduced the increase in pro‐inflammatory cytokines and ameliorated muscle atrophy by regulating Smad2/3, and activated the inhibited AKT signaling, which was suppressed by obesity." (PMID 39055231, 2024). "Two miRNAs up‐regulated in obesity and sarcopenia, miR‐424‐5p33 and miR‐92a‐3p,93 target Smad7, a strong inhibitor of the TGF‐β pathway, which in turn inhibits SMAD2/3." (PMID 34984856, 2022). "In contrast, regions accessible in monocytes from subjects with obesity harbored binding sites for regulatory factors such as STAT6 and SMAD2." (PMID 34195568, 2021). "Myostatin (GDF-8), frequently elevated in obesity and early T2D, exerts potent anti-anabolic and anti-oxidative effects and signals through the SMAD (mothers against decapentaplegic homolog) family of transcription factors, particularly SMAD2/3." (PMID 41515940, 2025). "Obesity-induced increases in HA deposition and CD44 and RHAMM expression are detrimental to the kidney via activation of the TGF-β1/Smad2/3, P38/JNK MAPK, and ROCK/ERK pathways, leading to glomerulopathy, tubular injury, inflammation, albuminuria, and elevated serum creatinine concentrations." (PMID 41301516, 2025). "Our results suggest a working model where obesity induces renal HA accumulation and CD44 and RHAMM expression, which activates the TGF-β1/Smad2/3, P38/JNK MAPK, and ROCK2/ERK/Akt pathways, promoting transcription of profibrotic and proinflammatory genes and contributing to the development of ORKP." (PMID 41301516, 2025). "The mechanism by which myostatin is upregulated in obesity has not yet been fully established; however, canonical myostatin signalling activates SMAD2/3 which represses muscle regulatory factors (MRFs), including MyoD." (PMID 37801203, 2024). "Therefore, platelet and neutrophil activation and tumor infiltration, TGF-β1/Smad2/3 signaling and HMGB1/RAGE signaling all play substantial roles in the obesity-driven aggressiveness of cancer, with each being a potential target for the anticancer actions of metformin." (PMID 36012397, 2022).
osteoporosis (15 papers, 2018 to 2025). A condition of reduced bone mass, with decreased cortical thickness and a decrease in the number and size of the trabeculae of cancellous bone (but normal chemical composition), resulting in increased fracture incidence. "In conclusion, these results show that ESW therapy promoted bone formation and prevented bone loss on osteoporosis through TGF-β/SMAD2 pathway and osteoblast differentiation can be more effectively promoted by ESW therapy with low energy flow density." (PMID 33841330, 2021). "CUR promotes osteoblast differentiation and matrix mineralization by enhancing the activity of the Transforming Growth Factor Beta (TGF-β)/Smad Family Member 2/3 (Smad2/3) signaling pathway, thereby improving the disordered trabecular bone structure caused by osteoporosis." (PMID 40469677, 2025). "Then, expression levels of SMAD2/3 and phosphorylated SMAD2/3 were notably increased induced by silenced CCNA1 in DEX-induced osteoporosis cells." (PMID 38454404, 2024). "Higenamine (HG) has been recognized as a promising candidate for treating osteoporosis through its influence on SMAD2/3 signaling." (PMID 38956429, 2024). "Our study discovered a long noncoding RNA that inhibited bone formation via miR-489-3P/SMAD2; it provided potential therapeutic insight for RNA-based therapy for osteoporosis." (PMID 35265818, 2022). "Therapeutically, local ESW therapy relieved bone loss and increased the number of bone trabecular in a rabbit osteoporosis model and promoted endogenous levels of SMAD2 protein expression." (PMID 33841330, 2021). "Consequently, HG emerges as a potential novel small-molecule drug to stimulate bone formation in osteoporosis via the Smad2/3 pathway." (PMID 38956429, 2024). "SMAD2 expression in OP bone tissue was higher than that in control group, implying that SMAD2 might play a significant role in osteoporosis." (PMID 37751585, 2023). "BM cells from the femurs and tibias of recipient mice injected with SM-EVs (from patients with tryptase >110 ng/ml) or SM-EVs from patients with osteopenia/osteoporosis showed markedly reduced mRNA expression levels of Alp, Runx2, Smad1/5, and to a lesser extent Smad2." (PMID 33953168, 2021). "Riveting on our findings, up‐regulation of miR‐497 or down‐regulation of LRG1 could activate TGF‐β signalling pathway as accompanied by increased TGF‐β1, Smad3, Smad4 and p‐Smad2/3 protein expression and reduced Smad7 protein expression in osteoporosis." (PMID 32975015, 2020). "Altogether, this study demonstrated for the first time the role of miRNA-181a/DUSP6 in the progression of osteoporosis via the ERK2 and SMAD2 signaling pathway." (PMID 34475393, 2021). "Interestingly, the expression of PARD6A and p-SMAD2, two genes enriched in the TGF-beta receptor signaling pathway, were significantly decreased in DEX-induced osteoporosis cells compared with that in control cells." (PMID 38454404, 2024).
idiopathic pulmonary fibrosis (13 papers, 2014 to 2026). Idiopathic pulmonary fibrosis (IPF) is a nonneoplastic pulmonary disease that is characterized by the formation of scar tissue within the lungs in the absence of any known cause. "SIRT2 is involved in the development of idiopathic pulmonary fibrosis (IPF) by regulating the Smad2/3 pathway." (PMID 39226168, 2024). "Numerous studies on treatment for idiopathic pulmonary fibrosis (IPF) focus on inhibiting the TGF-β pathway, including antagonizing TGF-β, inhibiting Smad2/3 phosphorylation, and activating Smad7." (PMID 39026235, 2024).